CD4 (CD4 molecule)
Diseases named in the same sentence as CD4 in open-access papers (continued):
Sharing a sentence is not in itself a finding about the gene and the disease.
tumor (continued). "The survivin reactive CD4+CD25- T cell precursor frequency was inversely associated with tumor survivin mRNA expression (p = 0.0028, r = −1.0, n = 6), and survivin tumor protein expression by IHC (p = 0.0295, r = −0.67, n = 10)." (PMID 25992291, 2015). "A study showed that MGL interacts with tumor-associated Tn antigens and efficiently internalized with antigens for presentation to CD4+ T cells." (PMID 26379663, 2015). "Tumor protection was also associated with differentiation of CD4+ and CD8+T-subpopulations and NK1.1+activation as measured by granzyme B expression, not detected in the control conditions at day 35 after tumor challenge." (PMID 26405163, 2015). "In HCC patients, increased infiltration of CD4+ T lymphocytes at the tumor margins has been reported to be associated with a lower recurrence rate and better prognosis." (PMID 25742141, 2015). "The presence of high tumor stroma infiltrating Foxp3 + CD4+ T cells was independently associated with improved NSCLC patients overall survival (P < 0.05)." (PMID 26604855, 2015). "It has been demonstrated, for instance, that in RCC high density CD4+ T-cell infiltrate is associated with unfavorable tumor characteristics and poor prognosis." (PMID 26317902, 2015). "Solid tumor development is facilitated by its microenvironment, which is composed of tumor associated macrophages (TAMs), DCs and Th2-deviated CD4+ T cells that release tumor-promoting cytokines." (PMID 26172457, 2015). "Contrasted with the possible tumor-promoting role of these cells in the progression of established tumors, the role of Foxp3+CD4+ T cells in initial tumor transformation caused by chronic inflammation remains elusive." (PMID 26604855, 2015). "We found that tumors that are high in both CD4+ and Foxp3+ T-cell content were associated with significantly higher average tumor PD-L1 expression (p = 0.014)." (PMID 26317902, 2015). "Increasing lipid levels and reducing numbers of CD8α+CD4- DCs were associated with increasing tumor burden which was associated with decreasing T cell proliferative responses to tumor antigen presentation in dLNs." (PMID 25886502, 2015). "Tumor preventive assays, based on the engraftment of TC-1 cells in mice, showed that the E6E7 multi-epitope protein induced a full preventive anti-tumor protection in wild-type mice, as well as in mice deficient in expression of CD4+ T cells and TLR4 receptor." (PMID 26390407, 2015). "The prognostic significance of tissue tumor-associated CD4+CD25+ T cells was observed in many previous studies." (PMID 26462021, 2015). "One of the most studied immune-suppressive cell types associated with tumor progression is regulatory T cells (Treg), characterized by their expression of CD4, high CD25 (CD4+CD25+CD127low/neg) as well as the transcription factor forkhead box P3 (FoxP3)." (PMID 26648934, 2015). "CD4+ Th2-polarized T-lymphocytes stimulate pulmonary metastasis by regulating the pro-tumor properties of tumor-associated macrophages." (PMID 25884510, 2015). "Our study demonstrated that tumor infiltrating Foxp3+CD4+T cells are associated with improved NSCLC patients’ survival." (PMID 26604855, 2015). "The other mechanism observed was the proportional reduction of tumor-associated CD8α+CD4- DCs as tumor size increased." (PMID 25886502, 2015). "To identify the genes encoding the tumor antigens recognized by CD4+ tumor-specific T cells, we used a genetic targeting expression system, which has been used to identify several MHC class II-restricted tumor antigens." (PMID 25993655, 2015). "It is likely that the declining proportions of cross-presenting CD8α+CD4- DCs and the presence of disabled and inappropriately activated lipid-laden tumor-associated DCs that migrated to dLNs account for this observation." (PMID 25886502, 2015). "The number of survivin reactive CD4+CD25- T cells is inversely associated with tumor survivin expression suggesting suppression of survivin responsive CD4+CD25- T cells." (PMID 25992291, 2015).
tumor (continued). "The increase in CD8+ T cells caused a significant decrease in CD4+/CD8+ ratio of the tumor tissues compared to the control tissues (P<0.0001)." (PMID 25605488, 2015). "Taken together, Loxoribin treatment leads to tumor regression, and the underlying mechanism involves modulation of the CD4+T cell proliferation and the suppressive activity of Tregs via DCs in a TLR7-dependent manner." (PMID 25593198, 2015). "Further functional analysis showed that significantly elevated frequencies of IFN-γ-producing cells were seen in tumor-associated CD4+ and CD8+ T cells from combination-treated mice." (PMID 26219551, 2015). "Further, the increase of Tregs in tumor infiltrating CD4 subset after 1D11 treatment negate the possibility that accumulation of Tregs in tumor was caused by the expansion of Tregs induced by TGFβ, or conversion of naïve CD4 cells into iTregs by TGFβ." (PMID 24416401, 2014). "MDSCs are known as tumor-associated suppressor cells and produce immunosuppression in opposition to various types of immune cells, including CD4+ T cell, CD8+ T cell, and NK cells." (PMID 25514597, 2014). "Since tumour resistance of Notch deficient skin is attributable mainly to CD4+ T cells, we examined the effect of intraperitoneal injections of blocking CD4 antibodies." (PMID 24843010, 2014). "Their depletion and adoptive transfer studies implicated a role for CD4+ T cells in mediating anti-tumor immunity." (PMID 24955247, 2014). "The antitumor effect of the IL-12 gene in several tumor models has been linked to activation of the cellular immune response, mainly activation of CD4+ T cells and CD8+ T cells." (PMID 24808638, 2014). "Tumour associated macrophages or myeloid-derived suppressive cells, CD4+ Foxp3+ Treg cells and Th17 cells and their associated cytokines Il-6, TNF, IL-1β, IL-23 and TGF-β are generally recognized as dominant tumour-promoting forces." (PMID 24963981, 2014). "The knock-out mice, lacking endogenous histamine, showed a predominance of Th1 cytokines and a lower level of Foxp3 (associated with CD4+CD25+ Tregs) expression compared to wild-type tumour-bearing mice." (PMID 25525463, 2014). "In accordance with previous findings suggesting an immunosuppressive role of FoxP3 in PDAC cells, high FoxP3 expression in tumor cells was associated with a low number of CD4+ T cells but elevated numbers of regulatory T cells as detected by FoxP3+ T cells." (PMID 24797069, 2014). "While Th1 cells are clearly associated with anti-tumor immunity, variable effects have been observed with other CD4+ T cell subsets, reviewed in Ref." (PMID 24782871, 2014). "Upon second immunization, hapten-specific B cells would have recognized the TNP-bound progressor cells and caused cross-activation with CD4+ T-cells, creating B-cells and CD4+ T-cells against the progressor tumor." (PMID 24949488, 2014). "More importantly, SLECs and DPECs were found in the tumor and these highly functional TILs greatly outnumbered the tumor-associated regulatory CD4 Treg population, resulting in much improved Teff : Treg ratios in the tumor microenvironment." (PMID 25328681, 2014). "Less obviously, CD4 T cells are also implicated in defective immunity to tumors, as CD4 regulatory T cells (Tregs) limit effector responses to tumor antigens." (PMID 24782861, 2014). "In vivo, a single low-dose of the DCIL-15 (not rIL-15)-based DC vaccines generated therapeutic antitumor immunity even in the CD4+ Th-deficient tumor-bearing hosts." (PMID 25941586, 2014). "Treatment-induced CD4 count suppression was found to be not only long-lasting, but also associated with earlier death secondary to tumor progression." (PMID 25268164, 2014). "iii) Low numbers of CD4+ (C) but high numbers of FoxP3+ (CD4+) T cells (F) were associated with high FoxP3 expression in tumor cells (O1)." (PMID 24797069, 2014).
tumor (continued). "Further functional analysis showed that significantly elevated frequencies ofIFN-γ-producing cells were seen in tumor-associated CD4+ andCD8+ T cells from combined mAb treated mice." (PMID 24502656, 2014). "Tumor protection was associated with a systemic immune response with memory and antigen specificity and required CD4+ cells and CD8+ T cells." (PMID 24586709, 2014). "PGE2 has also been shown to induce the production of IL-10 and directly suppress the production of proinflammatory cytokines by CD4+ T cells, implicating it as a key player in tumor-associated immunosuppression." (PMID 24698959, 2014). "In human colorectal cancer, very recently, the presence of Tregs and the consequent reduced response of anti-tumor CD4+ TH cells has been associated also to the progression of the diseases." (PMID 24600588, 2014). "In contrast, in those patients with triple negative receptor status only the tumour CD4 lymphocytic infiltrate was significantly associated with positive RUNX1 protein levels (P<0.05)." (PMID 24967588, 2014). "In preclinical studies with knockout mice it has been reported that CTLA-4 deficiency in CD4+CD25+ Treg impairs its suppressive function in tumor immunity." (PMID 23861693, 2013). "It has been shown that transfer of tumor-antigen specific CD4+ T cells in challenged but immune-deficient mice can cause complete tumor regression without the need of CD8+ T cell, NK cell or B cell assistance." (PMID 24205259, 2013). "Univariate and multivariate analysis demonstrated that the locoregional control of the tumor was positively associated with CD4+FOXP3+ regulatory cell infiltration." (PMID 23986759, 2013). "Specifically, in that study, they found that patients with high levels of tumor associated CD4+CD25+ T cells had a median survival of 10-20 months whereas those with medium or low levels had 40-50 and 60-70 median survival times, respectively." (PMID 24244610, 2013). "The depletion of Foxp3+ T cells and disruption of VEGF production on tumor cells mimic the phenotype seen in CD4+ T-cell specific Nrp1-deficient mice." (PMID 24324469, 2013). "CD4+ Tregs, Type 2 CD4+ T cells, Type 2 natural killer T cells, MDSCs, M2 or tumor-associated macrophages, B cells, and possibly mast cells promote tumor progression." (PMID 24833054, 2013). "Forkhead box protein P3 (FOXP3) expression in tumor infiltrating CD4+T cells is generally associated with an intrinsic capacity to suppress tumor immunity." (PMID 23977174, 2013). "Further studies are required to elucidate the molecular mechanisms underlying CD4+ T cell selection and CD4+ T cell function in the tumor microenvironment." (PMID 24013775, 2013). "The increased number of Treg cells can suppress CD4+T cell function in response to tumor-associated antigens." (PMID 24124529, 2013). "Avoiding immune destruction is a crucial hallmark because it has been shown that immune cells, CD4+ T cells in particular, are a required component for senescence, shutdown of angiogenesis and chemokine expression that result in sustained tumor regression." (PMID 23573174, 2013). "The presence of tumor cell-conditioned medium also causes conventional CD4+ T cells to transiently upregulate the expression of Foxp3 and TGF-β." (PMID 23720663, 2013). "In numerous murine tumor models increased frequencies of CD4+CD25high Treg cells seem to be a hallmark of tumor progression and metastasis." (PMID 22276195, 2012). "Although MHCII−/− mice with transferred polyclonal CD4+ T cells developed tumors, they had very low tumor burdens compared to mice receiving CD154-deficient or IL-2-deficient polyclonal CD4+ T cells." (PMID 23071696, 2012). "There were also higher frequencies of CD4+CD25int activated cells in the unaffected than in the tumor-associated mucosa." (PMID 22319577, 2012). "Treg were more frequent in the tumor tissue than unaffected tissue, and sometimes closely associated with CD4+ or CD8+ cells, possibly executing their regulatory effect." (PMID 22319577, 2012).
tumor (continued). "Bulky tumor was significantly associated with CD4 <100 cells/μL and large number of lesions was significantly associated with HIV-RNA ≥10,000 copies/mL." (PMID 23226197, 2012). "CD4+ iNKT-cells are known to provide a regulatory function by Th2 cytokine production and are implicated in inhibiting expansion of tumor antigen-specific CD8+ T-cells." (PMID 22396772, 2012). "Analysis of mechanisms underlying this effect revealed that IL-21 sustains CD4+ T cell infiltration in the tumor and peritumor areas and enhances the production of IL-6 and IL-17A as well as STAT3 activation." (PMID 23109839, 2012). "In the mouse model, depletion of CD4+CD25+ TReg cells using anti-CD25 antibody causes tumor regression, which correlated to the reduced number of TReg cells." (PMID 22481922, 2012). "Skin administration of imiquimod (Aldara® creme) as a single agent in tumor-bearing mice was associated with intracranial elevation of tumor infiltrating CD4+ T helper and CD8+ T killer lymphocytes." (PMID 22927956, 2012). "In clinical studies, CD4+ T cells have also been implicated in promoting the persistence and anti-tumor activity of antigen-specific CD8+ T cells in patients." (PMID 22279573, 2012). "It is thus less likely that the increased tumor protection observed in SH2D2A-deficient mice can be explained by more efficient IFN-γ production by the Id-specific CD4+ T cells." (PMID 23144743, 2012). "To determine the underlying tumor protection mechanism, we depleted CD4+, CD8+, or both populations at the effector phase, the time of tumor challenge." (PMID 22397502, 2012). "Impaired effector T-cell functions are often associated with increased numbers of CD4+CD25+FoxP3+ regulatory T cells in tumor-draining LN and tumor tissue." (PMID 22674057, 2012). "Corthay explored that CD4+ T cells mediate tumor rejection by producing IFN-γ to activate Mф-associated antitumor activity." (PMID 23145026, 2012). "Altogether, these results suggest that female DBY-specific CD4 T cells are able to potentiate CD8 T cell responses against an immunodominant tumor antigen arising from a spontaneous mutation." (PMID 22493742, 2012). "Tumor free TCR-transgenic SH2D2A-deficient mice had higher numbers of Id-specific single positive CD4+ thymocytes compared to TCR-transgenic wild-type mice." (PMID 23144743, 2012). "Tumor-associated macrophages (TAMs) are alternatively activated cells induced by interleukin-4 (IL-4)-releasing CD4+ T cells." (PMID 21939504, 2011). "Activation of tumor-specific cytotoxic T-lymphocytes (CTL) requires presentation of tumor-associated antigens (TAAs) primarily by dendritic cells (DC), in addition to the helper functions of CD4+ cells." (PMID 22029859, 2011). "The phenotypic characterization of TICs revealed that α-TEA caused an increase in the frequency of activated CD4+ T cells in the tumor microenvironment on day 18 post-tumor cell injection." (PMID 21232138, 2011). "In humanized mice which have been reconstituted with autologous DCs and implanted with tumor cells it has been shown that adoptive transfer of autologous CD4+ T cells is associated with an increase in tumor mass." (PMID 21281484, 2011). "In humans, MGL interacts with terminal GalNac epitopes, e.g., tumour associated Tn antigens, and can efficiently internalise antigen for presentation to CD4+ T-cells." (PMID 24212951, 2011). "Second, whole tumor lysate provides a rich array of tumor-associated antigens for both CD4+ and CD8+ T cells." (PMID 22194898, 2011). "In a pilot study of 15 tumor biopsies from 7 tremelimumab-treated patients, clinical response was associated with increased tumor infiltration by CD8+ TILs whereas a more variable association was found with tumor infiltration of CD4+ TILs." (PMID 22123319, 2011).
tumor (continued). "Cancer vaccines seek to treat malignancies by approaches that induce presentation of tumor-associated antigens (TAAs) in contexts that elicit potent CD4+ and CD8+ T-cell responses and break the tolerance of the host immune system to tumor growth." (PMID 21689407, 2011). "Some studies have associated that the predominance of CD4+ T-lymphocytes in the tumor site is capable of "controlling" the expansion of CD8+ T-lymphocytes, thus inhibiting an effective antitumor response." (PMID 20525350, 2010). "The presence of Foxp3+ regulatory CD4+ T cells in tumor lesions is considered one of the major causes of ineffective immune response in cancer." (PMID 21049016, 2010). "Based on these mouse cancer models, tumor-associated B7-H3 seems to preferentially regulate CD4-independent induction of CD8+ CTL responses." (PMID 21127709, 2010). "Women presented with lower CD4 T-cell counts at diagnosis, had frequent orofacial KS, and were less likely to have tumor-associated edema or nodular lesions than men." (PMID 21103057, 2010). "For example, in the same K14-HPV16 transgenic mice used in this study, deficiency of CD4+ T cells delays neoplastic progression and lowers tumor incidence." (PMID 21085595, 2010). "There are increasing evidences that tumor-derived soluble factors promote the induction of tolerance through the generation of CD4+ CD25highFoxp3+ Treg subset, which is linked to compromised immune responses in patients with advanced cancer." (PMID 20182533, 2009). "Depletion in CD4+ T cell populations by tumor supernatant prompted us to investigate the underlying cause." (PMID 19812686, 2009). "The tumour CD4+ T-lymphocytic infiltrate was directly associated with CD8+ (P<0.001) but not with C-reactive protein (P=0.556)." (PMID 17024120, 2006). "The tumour COX-2 expression was directly associated with the tumour CD4+ (P<0.01) and CD8+ (P<0.05) T-lymphocytic infiltrate and weakly with C-reactive protein (P=0.068)." (PMID 17024120, 2006). "We were interested in generating HLA-DR*1101 tetramers to characterise CD4+ T cell responses to several peptide epitopes derived from either environmental or tumour-associated antigens." (PMID 16329759, 2005). "On univariate analysis, both C-reactive protein concentrations (P<0.001) and percentage tumour volume of CD4+ (P<0.05) T-lymphocytes were associated with cancer-specific survival." (PMID 15700032, 2005). "The results of the present study show that low tumour CD4+ T-lymphocyte infiltration is associated with elevated C-reactive protein concentrations and both predict poor cancer-specific survival." (PMID 15700032, 2005). "Using viral vectors with genes encoding the full-length tumour antigens to transfect autologous DCs to activate both CD4+ and CD8+ T cells makes the typing of HLA haplotypes unnecessary." (PMID 15083197, 2004). "IFN-γ and IL-2, secreted by CD4 + Th1 cells, trigger the activation of DCs and enhance the cross-presentation of tumor-associated antigens (TAAs), thereby priming anti-tumor CD8 + T cells and supporting their differentiation into mature CD8 + cytotoxic T lymphocytes (CTLs)." (PMID 41582199, 2026). "Our present study demonstrated that CDKN2A expression was positively correlated with the infiltration levels of CD4+ T cells, macrophages, and cancer-associated fibroblasts, suggesting its apparent potential role in promoting tumor progression through remodeling the immune microenvironment." (PMID 41614944, 2026). "Notably, a notable correlation was identified between SDC1 levels and key components within the tumor microenvironment, including CD4+/CD8 + T lymphocytes, cancer-associated fibroblasts (CAFs), and myeloid-derived suppressor cells (MDSCs)." (PMID 42098527, 2026). "Consequently, the platform significantly promotes dendritic cells maturation, enables epigenetic reprogramming of tumor‐associated macrophages (TAMs), and restores CD4+/CD8+ T‐cells functionality." (PMID 41090529, 2026).